MARK4 (microtubule affinity regulating kinase 4)
Description:
Serine/threonine-protein kinase. Phosphorylates the microtubule-associated protein MAPT/TAU. Also phosphorylates the microtubule-associated proteins MAP2 and MAP4. Involved in regulation of the microtubule network, causing reorganization of microtubules into bundles. Required for the initiation of axoneme extension during cilium assembly. Regulates the centrosomal location of ODF2 and phosphorylates ODF2 in vitro. Plays a role in cell cycle progression, specifically in the G1/S checkpoint. Reduces neuronal cell survival. Plays a role in energy homeostasis by regulating satiety and metabolic rate (By similarity). Promotes adipogenesis by activating JNK1 and inhibiting the p38MAPK pathway, and triggers apoptosis by activating the JNK1 pathway (By similarity). Phosphorylates mTORC1 complex member RPTOR and acts as a negative regulator of the mTORC1 complex, probably due to disruption of the interaction between phosphorylated RPTOR and the RRAGA/RRAGC heterodimer which is required for mTORC1 activation. Involved in NLRP3 positioning along microtubules by mediating NLRP3 recruitment to microtubule organizing center (MTOC) upon inflammasome activation.
Synonyms: KIAA1860; MARKL1; Nbla00650; FLJ90097; PAR-1D; MARK4L; MARK4S; MARKL1L
Tractability: Small molecule: a structure with a bound ligand is known; a high-quality ligand is known; it belongs to a druggable protein family. PROTAC: it is named in the literature on targeted protein degradation; UniProt records ubiquitination sites on it; ubiquitination databases record sites on it; its protein half-life has been measured; a small molecule that binds it is known.
Target class: Protein Kinase; Kinase; CAMK protein kinase group; CAMK protein kinase MARK subfamily; CAMK protein kinase CAMK1 family; Enzyme
Gene: Protein-coding gene on chromosome 19 (45,079,288 to 45,305,284, forward strand). Ensembl gene ENSG00000007047.
Subcellular location: Cytoplasm, cytoskeleton, microtubule organizing center, centrosome; Cytoplasm, cytoskeleton, microtubule organizing center; Cytoplasm, cytoskeleton, cilium basal body; Cytoplasm, cytoskeleton, cilium axoneme; Cytoplasm; Cell projection, dendrite
Subcellular location (Human Protein Atlas): Cytosol
Pathways (Reactome):
Organelle biogenesis and maintenance: Anchoring of the basal body to the plasma membrane
Gene Ontology:
Molecular function: cytoskeletal anchor activity; gamma-tubulin binding; microtubule binding; protein binding; protein serine/threonine kinase activity; tau-protein kinase activity; ATP binding; tau protein binding; ubiquitin binding; protein kinase activity; protein serine kinase activity
Biological process: cilium organization; microtubule bundle formation; microtubule cytoskeleton organization; nervous system development; positive regulation of cell cycle; positive regulation of cilium assembly; positive regulation of NLRP3 inflammasome complex assembly; positive regulation of protein localization to centrosome; protein phosphorylation; regulation of centrosome cycle; intracellular signal transduction; positive regulation of programmed cell death
Cellular component: centrosome; ciliary basal body; cytoplasm; cytosol; dendrite; gamma-tubulin complex; microtubule cytoskeleton; microtubule organizing center; midbody; neuron projection; microtubule; axoneme
Genetic constraint (gnomAD): Loss-of-function variants: 19 observed, 77.15 expected, observed/expected ratio (o/e) 0.25, 90% interval 0.17 to 0.36. The upper end of that interval is the gene's LOEUF score, 0.36, which puts it in group 1 of 6, group 1 being the genes least tolerant of losing a copy. Missense variants: 769 observed, 1,027.5 expected, observed/expected ratio (o/e) 0.75, 90% interval 0.7 to 0.79. Synonymous variants: 435 observed, 418.87 expected, observed/expected ratio (o/e) 1.04, 90% interval 0.96 to 1.12.
Homologues: Orthologues: chimpanzee MARK4 (99% identical), macaque MARK4 (99% identical), pig MARK4 (99% identical), guinea pig MARK4 (98% identical), rat Mark4 (98% identical), mouse Mark4 (98% identical), zebrafish mark4a (67% identical), zebrafish mark4b (67% identical), tropical clawed frog mark4 (64% identical). Paralogues in human: MARK3 (63% identical), MARK1 (59% identical), MARK2 (56% identical).
Diseases named in the same sentence as MARK4 in open-access papers:
MARK4 is named in the same sentence as 54 diseases in open-access papers, as found by Europe PMC text mining. Sharing a sentence is not in itself a finding about the gene and the disease. The quoted sentences say what the papers report.
breast carcinoma (23 papers, 2016 to 2025). "MARK4 has recently been implicated in breast cancer cell proliferation and migration via blocking Hippo signaling." (PMID 35936719, 2022). "The MARK4 protein, which is closely linked to breast cancer, has a high affinity for RA." (PMID 40427522, 2025). "RA successfully targeted MARK4, a kinase implicated in the progression of cancer, indicating that it may be a suitable therapeutic target for breast cancer." (PMID 40427522, 2025). "MARK4 is linked to breast cancer growth and metastasis via Hippo signaling." (PMID 35936719, 2022). "Isatin-triazole hydrazones, were also described as anticancer agents as well as potent inhibitors of Microtubule affinity-regulating kinase 4 (MARK4), known to induce proliferation and migration of cells in breast cancer, also associated with hepatocellular cancer." (PMID 33614708, 2020). "LINC00673, which is upregulated by YY1, exerts oncogenic functions in breast cancer by sponging miR-515-5p and subsequently upregulates MARK4 expression, and inhibits the Hippo signaling pathway." (PMID 36309503, 2022). "It has been shown to promote the proliferation of breast cancer by sponging miR-515-5p to regulate MARK4 expression and inhibit the Hippo signaling pathway." (PMID 34733328, 2021). "For example, MARK4 expression inhibited Hippo signaling and facilitated breast cancer cell proliferation and metastasis." (PMID 34037089, 2021). "Pardo and colleagues also suggested that miR-515-5p overexpression inhibited tumour cell metastasis through targeting MARK4 in breast cancer and non-small cell lung cancer model." (PMID 34774083, 2021). "Simultaneously, we noticed that one of these candidate miRNAs, miR-515-5p, has been found to dramatically inhibit breast cancer cell proliferation and to control cancer cell migration through MARK4 regulation in breast cancer." (PMID 31623640, 2019). "We found that compared to control cells, breast cancer cells with LINC00673 knockdown had significantly reduced MARK4, YAP, and TAZ expression and increased YAP phosphorylation levels in the Hippo signaling pathway." (PMID 31623640, 2019). "In summary, we demonstrated that LINC00673 promotes breast cancer cell proliferation via the Hippo signaling pathway by regulating MARK4." (PMID 31623640, 2019). "Recently, MARK4 has been reported to promote breast cancer cell proliferation and migration through the inhibition of hippo signalling." (PMID 28842631, 2017). "To date, MARK4 has been found to contribute to the development of hepatocellular carcinomas, gliomas, prostate cancer and breast cancer." (PMID 28122348, 2017). "But a recent study showed that miR-515-5p inhibits cancer cell migration and metastasis by targeting microtubule affinity regulating kinase 4 (MARK4) in breast cancer." (PMID 27092493, 2016). "We analysed the overall survival (months) of a cohort of patients with metastatic lung or breast cancer and correlated this with the levels of MARK4 mRNA present in their tumours." (PMID 26882547, 2016). "Furthermore, in MDA-MB-231 breast cancer cells, RA suppressed MARK4 (microtubule affinity-regulating kinase 4) activity, which led to dose-dependent apoptosis." (PMID 40427522, 2025). "MARK4 is connected to Hippo signaling, which plays a role in breast cancer growth and metastasis." (PMID 35936719, 2022). "Then, miR-515-5p was chose to verify that it could bind to LINC00673 and MARK4 in breast cancer cells." (PMID 34296748, 2021). "LINC00673 enhances breast cancer cell proliferation by miR-515-5p/MARK4 axis." (PMID 34774083, 2021). "Moreover, YY1-activated LINC00673 has been revealed to promote proliferative activity of breast cancer cells via regulating MARK4 through sponging miR-515-5p." (PMID 32272940, 2020). "MARK4 plays an important role in breast cancer proliferation and migration through hippo signaling." (PMID 32587267, 2020). "In addition, MARK4 regulates miR- 515-5p, that found to be involved in breast cancer cell proliferation and migration." (PMID 32587267, 2020).
breast carcinoma (continued). "Moreover, in luminal B breast cancer and in normal breast epithelial cells, miR‐515‐5p levels were significantly inversely correlated with MARK4 expression and a similar trend existed in the case of luminal A and basal breast cancer." (PMID 26882547, 2016). "As MARK4 was so predominantly down‐regulated by miR‐515‐5p in breast cancer cells, we questioned whether silencing MARK4 would mimic the effect of miR‐515‐5p on cell morphology and in cell migration assays." (PMID 26882547, 2016). "To test our hypothesis that MARK4 down‐regulation was the mechanism through which miR‐515‐5p affected breast cancer cell migration, we tested whether overexpressing MARK4 in miR‐515‐5p‐transfected cells could rescue the reduced cell motility." (PMID 26882547, 2016). "Considering the critical role of the Hippo/YAP signaling pathway in KMT5A/SNIP1/MARK4-driven breast cancer progression and metastasis, the effects of verteporfin treatment combined with KMT5A-depletion on breast cancer metastasis were assessed." (PMID 35449131, 2022). "Microtubule affinity-regulating kinase 4 (MARK4) acts as a negative regulator of Hippo kinase, and abrogation of MARK4 attenuates cell growth and migration in breast cancer cells." (PMID 34083586, 2021). "MARK4, a member of the microtubule affinity regulating kinase (MARK) family, has been reported to promote proliferation via the Hippo signaling pathway in breast cancer cells." (PMID 31623640, 2019). "To further validate the role of MARK4 in the migration of breast cancer cells, we performed random migration experiments in migratory MDA‐157 breast cancer cells and found that MARK4 silencing significantly reduced their motility." (PMID 26882547, 2016). "First, to assess whether c-MYC directly mediates MARK4 transcription, MARK4 expression was detected in c-MYC-knockdown breast cancer cells, where its expression was significantly downregulated in MDA-MB-231 and BT549 cells." (PMID 35449131, 2022). "Notably, the reduction in MARK4 and YAP/TAZ and the increase phosphorylated YAP protein expression was also abolished by miR-515-5p inhibitors in breast cancer cells transfected with si-LINC00673." (PMID 31623640, 2019). "Moreover, we found that MARK4 was significantly overexpressed in human breast cancer tissues with shorter OS, and a positive correlation was found between LINC00673 and MARK4." (PMID 31623640, 2019).
Alzheimer disease (20 papers, 2014 to 2025). A progressive, neurodegenerative disease characterized by loss of function and death of nerve cells in several areas of the brain leading to loss of cognitive function such as memory and language. "Dysregulation of MARK4 has been associated with various diseases, including different types of cancer and Alzheimer’s disease." (PMID 40332117, 2025). "Numerous studies have shown that Mark4 is closely associated with the occurrence of diverse diseases, including cancer, Alzheimer’s disease, and cardiovascular disease." (PMID 38301049, 2024). "Microtubule-affinity regulating kinase 4 (MARK4) is a tau kinase genetically linked to risks of Alzheimer’s disease." (PMID 38712317, 2024). "PAR-1 also phosphorylates Tau at the S262 and S356 residues, as its homolog MARK4 does, which is implicated in Alzheimer’s disease-related tau toxicity." (PMID 37550059, 2023). "In lieu of this vital role in tau pathology, a hallmark of Alzheimer’s disease (AD), MARK4 is a druggable target to treat AD and other neurodegenerative disorders (NDs)." (PMID 35889524, 2022). "over-expression of MARK4 is associated with obesity and diabetes, Alzheimer’s diseases (AD) and metastatic breast carcinomas." (PMID 32587267, 2020). "Microtubule affinity-regulating kinase (MARK4) plays a key role in Alzheimer’s disease (AD) development as its overexpression is directly linked to increased tau phosphorylation." (PMID 32443670, 2020). "MARK4 overexpression hyperphosphorylates the microtubule-associated protein Tau, which causes its detachment from microtubules and eventually develops neurofibrillary tangles, a pathogenic hallmark of Alzheimer’s disease." (PMID 37550059, 2023). "Hyperphosphorylation of tau is a key pathological feature in Alzheimer’s disease (AD), and studies have established the critical role of MARK4 in this event." (PMID 37795023, 2023). "Increased expression of MARK4 has been shown in Alzheimer’s disease (AD), and in vitro studies suggest MARK4 can potentiate tau aggregation." (PMID 37391420, 2023). "MAP (Mitogen-activated protein kinase)/Microtubule Affinity Regulating Kinase 4 (MARK4) is a Ser-Thr kinase that plays a key role in early tau phosphorylation, leading to Alzheimer’s disease." (PMID 34681645, 2021). "Many studies described the importance of MARK4 in obesity, diabetes, Alzheimer’s diseases (AD), and metastatic breast carcinomas." (PMID 32443670, 2020). "This study focused on the abnormal phosphorylation of tau and its aggregation process, characteristic of Alzheimer’s disease, and aimed to compare the morphology and formation process of phosphorylated tau aggregates produced by four kinases: Cdk5/p25, GSK3β, MARK4, and p38α." (PMID 41155414, 2025). "Microtubule affinity-regulating kinase 4 (MARK4) has been genetically and pathologically associated with Alzheimer’s disease and reported to enhance tau phosphorylation and toxicity in Drosophila and mouse traumatic brain-injury models but not in mammalian tauopathy models." (PMID 38712317, 2024). "Another study reported nine somatic mutations in the amyloid beta precursor protein (APP), sortilin-related receptor 1 (SORL1), nicastrin (NCSTN) and microtubule affinity-regulating kinase 4 (MARK4) genes in patients with Alzheimer’s disease by next-generation sequencing (NGS)." (PMID 37834279, 2023). "In addition, MARK4 has been explored as a potential drug target for cancer and Alzheimer’s disease therapy." (PMID 34681645, 2021). "Microtubule affinity regulating kinase 4 (MARK4) participates in the development of Alzheimer’s disease by hyperphosphorylating tau protein and is a drug target for Alzheimer’s disease." (PMID 38671841, 2024). "Based on gene enrichment testing in FUMA, both MARK4 and PPP1R37 have been reported in “Alzheimer’s disease or HDL levels” in the GWAS catalog." (PMID 37391420, 2023).
Alzheimer disease (continued). "Among the top 20 associated genes, the gene-set enrichment analysis showed that the GWAS catalog gene-set of Alzheimer’s disease or pleiotropy had 4 genes (GEMIN7, MARK4, PPP1R37, and NKPD1) overlapped (p = 1.74 × 10−7, adjusted-p = 3.16 × 10−4)." (PMID 37391420, 2023).
Obesity (9 papers, 2016 to 2025). Accumulation of substantial excess body fat. "Recently, the researchers found that Mark4 knockout mice increased their appetite, activity, and metabolic rate to resist obesity caused by a high-fat diet." (PMID 32326642, 2020). "In addition, patients of both MARK4 groups frequently displayed several cardiovascular risk factors including obesity (body mass index [BMI]: 28.6 ± 4.5 kg/m2), diabetes mellitus, hyperlipidemia, and arterial hypertension." (PMID 40332117, 2025). "Our previous research showed increased appetite, activity, and metabolic rate in Mark4 knockout mice against obesity induced by high-fat diet." (PMID 32326642, 2020). "Our previous studies showed that Mark4 knockout mice were protected from obesity and insulin resistance (IR) induced by HFD6." (PMID 26888669, 2016). "Recently, Mark4 knockout mice is resistance to high-fat diet (HFD) induced obesity and insulin resistance." (PMID 26888669, 2016). "Other studies have shown that MARK4 knockout mice are less likely to suffer from obesity, which is mainly reduced by increasing the metabolic rate, to potentially reduce insulin resistance in mice and promote fat cell apoptosis, inflammation, and oxidative stress." (PMID 38839927, 2024). "In addition, Mark4 promoted oxidative stress and mitochondrial dysfunction by activating NF-κB and inhibiting AMPK pathways in obesity-associated disorders." (PMID 38301049, 2024). "By activating JNK1 and blocking the p38MAPK pathways, MARK4 promotes obesity and cell death." (PMID 35936719, 2022). "Several studies have shown that MARK4 knockout mice is protected from obesity and insulin resistance (IR) induced by high-fat diet (HFD), suggesting a novel role of MARK4 in modulating glucose homeostasis and energy metabolism." (PMID 35052845, 2022).
glioma (7 papers, 2016 to 2022). A benign or malignant brain and spinal cord tumor that arises from glial cells (astrocytes, oligodendrocytes, ependymal cells). "MARK4 is reportedly upregulated in liver cancer, gliomas, and glioblastomas; however, the LKB1–MARK4 axis is reported to function as both an agonist and antagonist of Hippo signaling, suggesting cell-type dependent regulation of the LKB1–MARK4 axis." (PMID 35017636, 2022). "Glioma progression is slowed when MARK4 expression is inhibited." (PMID 35936719, 2022). "Inhibiting MARK4 expression slows the progression of gliomas." (PMID 35936719, 2022).
diabetes (6 papers, 2020 to 2025). "Thus, this study explored the MARK4 inhibitory potential of Mtf using various computational and experimental approaches and will provide a platform to decipher the association of diabetes and neurodegenerative disorders (NDs)." (PMID 35889524, 2022). "The present study provides an additional axis towards the utilization of Mtf as MARK4 inhibitor targeting diabetes with NDs." (PMID 35889524, 2022). "MARK4 is thus a well-known therapeutic target in the fields of cancer, diabetes, and neurological disorders." (PMID 35936719, 2022). "MARK4 is an important kinase that plays a vital role in disease therapeutics ranging from NDs to diabetes due to various important roles performed by this kinase." (PMID 35889524, 2022). "Microtubule affinity regulating kinase 4 (MARK4) is a Ser/Thr kinase, considered as a potential drug target for cancer, diabetes and neurodegenerative diseases." (PMID 35520423, 2020). "The design and development of potential MARK4 inhibitors are of great significance to address cancer, diabetes, and AD therapy." (PMID 32443670, 2020). "However, whether MARK4 intervention can also reduce myocardial apoptosis and myocardial oxidative stress, alleviate mitochondrial dysfunction and promote myocardial lipid metabolism in other diabetes models, which needs further research in the future." (PMID 38839927, 2024).